INS (insulin)
Diseases named in the same sentence as INS in open-access papers (continued):
Sharing a sentence is not in itself a finding about the gene and the disease.
Insulin resistance (continued). "In the current investigation, the laser acupuncture group demonstrated a significantly higher reduction in insulin levels than control group, indicates that insulin sensitivity has improved and insulin resistance has reduced." (PMID 39138739, 2024). "T1DM is a chronic, immune-mediated disease characterized by the destruction of insulin-producing β-cells in the pancreas, while T2DM is primarily characterized by insulin resistance and impaired insulin secretion." (PMID 38659573, 2024). "Higher plasma insulin levels, which occur as a result of insulin resistance, activate HMG-CoA reductase activity, and up-regulation of hepatocyte LDL receptors, leading to increased hepatic cholesterol secretion." (PMID 38238700, 2024). "Fasting hyperglycemia occurs as a result of inadequate basal insulin secretion to maintain normal fasting plasma glucose concentrations or as a result of the appearance of insulin resistance." (PMID 39469577, 2024). "The effect of inhibition decreased insulin resistance, decreased liver steatosis, enhanced insulin-induced suppression of hepatic glucose production, and impeded the development of insulin resistance after high-fat feeding." (PMID 38399444, 2024). "Insulin resistance was estimated using mathematical models based on fasting insulin and glucose levels, which were determined by a homeostasis model assessment for insulin resistance (HOMA‐IR)." (PMID 38626370, 2024). "Studies suggest that inhibition of PTP1B and increased serum levels of irisin can lead to improvement in insulin resistance, as well as insulin and blood glucose levels." (PMID 38431555, 2024). "Insulin resistance is a pathological-physiological state characterized by decreased insulin sensitivity in peripheral tissues." (PMID 38715070, 2024). "There was a significant difference (p < 0.05) between the obese and lean PCOS patients when the biochemical parameters like fasting insulin, fasting glucose, and homeostatic model assessment of insulin resistance (HOMA-IR) were compared." (PMID 38567220, 2024). "The present study examined the insulin-sensitizing properties of decoction extracts of C. prophetarum in L6 myotubes in which insulin resistance was induced by PA (0.75 mM)." (PMID 39795155, 2024). "Insulin resistance and insufficient insulin secretion are also determinants of HIP, and in theory, smoking during pregnancy encourages HIP." (PMID 39274361, 2024). "Insulin resistance is a disorder where the cells of the body especially fat, muscle and liver turn out to be less receptive to the insulin effects." (PMID 38371502, 2024). "The fatty growth of internal organs and the subsequent β-cell hyperplasia lead to abnormal insulin secretion, exacerbating insulin resistance, with the process repeating in a circular pattern." (PMID 38792339, 2024). "In metabolic syndrome, insulin resistance is also a consequence of sustained inflammation in peripheral tissue; insulin has a neuroprotective effect and by regulating synaptic plasticity it is fundamental for optimal cognitive functioning." (PMID 39350374, 2024). "The impairment of HMGCR activity, induced by statins, can have adverse effects on insulin sensitivity and increase insulin resistance." (PMID 38416767, 2024). "In T2DM, insulin resistance is responsible for increased glucose production in the liver and decreased glucose uptake in muscle and adipose tissue at a set insulin level." (PMID 38891933, 2024). "Yet, values of insulin resistance and insulin sensitivity at study entry were already predictive of the progression to diagnosis." (PMID 37914981, 2024). "In the T2DM KK-Ay obese mouse model, TRG reduced the plasma levels of glucose and insulin and improved glucose tolerance and the insulin resistance index calculated by the homeostasis model assessment of insulin resistance (HOMA-IR)." (PMID 38542359, 2024).
Insulin resistance (continued). "Intra-individual variability is generally higher for insulin-based indices than for C-peptide-based measurements, which is also reflected by a high heterogeneity across surrogate measures of insulin resistance." (PMID 39013634, 2024). "The altered expression of genes involved in insulin signaling, glucose transport, and inflammatory responses can contribute to the development and exacerbation of insulin resistance and hyperglycemia, hallmarks of GD." (PMID 39519193, 2024). "Apelin, as an adipokine, can promote insulin secretion, increase insulin sensitivity, and improve insulin resistance." (PMID 39014438, 2024). "As expected, the AOb mice developed peripheral insulin resistance with reduced insulin-stimulated glucose uptake into adipose tissue, compared to both the WL and chow control groups." (PMID 38961153, 2024). "Normoglycemia is targeted through changes in diet and lifestyle initially, but in case of profound insulin resistance, pharmacological medication (primarily insulin) is recommended as part of GDM treatment." (PMID 39497166, 2024). "Type 2 diabetes (T2D) is a complex and multifactorial metabolic disease characterized by insulin resistance and insufficient insulin secretion." (PMID 38427644, 2024). "As T2D progresses, blood sugar levels rise because pancreatic β-cells are unable to secrete sufficient insulin to overcome insulin resistance." (PMID 39072276, 2024). "Cancer has previously been shown to lead to marked insulin resistance due to blocked insulin-stimulated glucose transport and abolished insulin-induced phosphorylation of AS160Thr642 at multiple phosphorylation sites." (PMID 38110544, 2024). "One of the main players in theinter-relationship between obesity and insulin resistance is adiponectin, an insulin sensitizer produced from adipose tissue that alsohappens to be a significant risk factor for type 2 diabetes." (PMID 38497075, 2024). "Insulin resistance is characterized by insulin insensitivity in peripheral tissues and shares pathological pathways in common with hypertension." (PMID 39217344, 2024). "PTP1B is known to exert a negative regulatory effect on leptin and insulin signaling, which has implications for insulin resistance and metabolic disorders." (PMID 38247843, 2024). "Randomized controlled trials that assessed the effects of vitamin D supplementation in women with PCOS, on fasting glucose, fasting insulin, glycated haemoglobin (HbA1c) or homeostatic model assessment for insulin resistance (HOMA-IR) were included." (PMID 39276209, 2024). "The accumulation of IMAT has been suggested to impair insulin diffusion through the muscle interstitial space, leading to insulin resistance in dogs." (PMID 38788527, 2024). "These lipids are stored as triglycerides in fat cells and less efficient ability of insulin to inhibit breakdown (antilipolysis) and/or stimulate synthesis of the triglycerides could elevate the circulating fatty acid levels and, in turn, cause insulin resistance." (PMID 38491191, 2024). "A prolonged period of T2DM is often accompanied by a gradual reduction of insulin production due to pancreatic β-cell failure, which in turn increases insulin resistance, making it more difficult to manage blood glucose." (PMID 38664794, 2024). "GH is a known antagonist of insulin action, impairing the ability of insulin to stimulate glucose uptake and contributing to insulin resistance." (PMID 39568151, 2024). "The intricate relationship between BMI, daily insulin doses, insulin resistance, severe hypoglycemia, and A1C has garnered attention." (PMID 38553464, 2024). "Prolonged systemic exposure to even mildly elevated levels of LPS can trigger immune responses and activate inflammation pathways, which impedes insulin signaling, in turn, and contributes to the development of insulin resistance." (PMID 39063539, 2024).
Insulin resistance (continued). "Specifically, around 16 weeks, insulin resistance begins to increase, and total daily insulin doses increase linearly 5% per week through the 36th week." (PMID 38592281, 2024). "To assess the extent of insulin resistance in the experimental models, we performed the insulin tolerance test after i.p. insulin administration." (PMID 38673735, 2024). "One prominent aspect is the development of insulin resistance, where cells become less responsive to insulin, impairing glucose homeostasis." (PMID 38977131, 2024). "Insulin resistance (IR) refers to the reduced ability of insulin to mediate metabolic effects like glucose uptake and lipolysis, requiring higher insulin levels." (PMID 39665024, 2024). "One of the key characteristics of insulin resistance is impaired signal transduction of the insulin/PI3K/Akt signaling pathway, which leads to an increase in GSK-3β." (PMID 38683825, 2024). "Insulin resistance reduces insulin release, results in low glucose uptake, and leads to hyperglycemia, which, in turn, causes DM." (PMID 39493064, 2024). "The process of insulin resistance mainly occurs in insulin-sensitive tissues, namely, the liver, muscle, and adipose tissue, mainly due to the dysregulation of the IS." (PMID 39595541, 2024). "Absolute/decreases in fasting plasma LEAP2 positively correlated with absolute/decreases in body mass index, glycated hemoglobin A1c, fasting plasma glucose, serum insulin, homeostatic model assessment for insulin resistance, and serum triglycerides." (PMID 39659543, 2024). "Several studies have demonstrated that EDCs can induce oxidative stress and inflammation, leading to elevated in vivo levels of inflammatory cytokines, which subsequently impact insulin signaling and contribute to insulin resistance and T2DM." (PMID 39596180, 2024). "Increased insulin secretion was also reported after the consumption of a Westernized diet, which preceded peripheral insulin resistance." (PMID 38257161, 2024). "Cornelian cherry has been shown to enhance the expression of insulin signalling genes in adipocytes, while increasing the expression of PPARγ, therefore alleviating insulin resistance and exerting a beneficial effect on cellular metabolism." (PMID 38999920, 2024). "His subsequent A1C was 5.5, C-peptide 1.67, fasting insulin 8, and fasting glucose 87, reflective of insulin resistance score 1.7, within normal limits." (PMID 39135763, 2024). "The primary mechanism of PTDM is based on increased insulin resistance, impaired insulin production as a result of pancreatic β-cell damage and uncontrolled glucagon release." (PMID 39204092, 2024). "Type 2 diabetes is characterized by hyperglycemia due to insufficient insulin secretion of pancreatic β cells in the case of overnutrition or insulin resistance." (PMID 38921478, 2024). "Vitamin D indirectly affects insulin secretion by reducing inflammatory responses and improving insulin resistance." (PMID 39749014, 2024). "In T2DM patients, insulin is still produced, but the body is unable to use it properly due to insulin resistance." (PMID 39839113, 2024). "Neurons with Alzheimer's exhibit insulin resistance, although insulin has a positive impact on bioenergetics and brain metabolism." (PMID 39493064, 2024). "Continuous hyperglycemia promotes insulin resistance in peripheral tissues, leading to decreased sensitivity of cells to insulin." (PMID 39165284, 2024). "RS also protects the pancreatic β-cells, increases insulin secretion and glucose homeostasis, decreases insulin resistance, and ameliorates metabolic disorders." (PMID 38903985, 2024). "Myostatin, a growth factor secreted by skeletal muscle, plays a pivotal role in regulating insulin signaling and insulin resistance." (PMID 38659573, 2024).
Insulin resistance (continued). "Previous reports indicate that plant secondary metabolites improve hyperglycemia and insulin resistance mainly by regulating lipid and protein metabolism pathways, insulin signaling pathways, anti-inflammatory responses, and antioxidant stress." (PMID 39045049, 2024). "Mice with cardiac hypertrophy exhibited a higher degree of insulin resistance than the control group, as demonstrated by lower glucose uptake after insulin infusion." (PMID 39125938, 2024). "It reduced body weight significantly, lowered insulin and blood sugar levels, improved insulin resistance, and decreased serum amylase and lipase levels." (PMID 38961451, 2024). "The appearance of insulin resistance usually consists of impaired glucose disposal at the level of insulin-resistant tissues, primarily skeletal muscle." (PMID 39768947, 2024). "Chronically increased levels of insulin decrease circulating IGFBP-1, which correlates closely with whole-body and hepatic insulin resistance as well as with metabolic dysfunction-associated steatotic liver disease (MASLD)." (PMID 38928106, 2024). "The study reported that BLE significantly reduced triglycerides by 35%, insulin by 22%, and insulin resistance by 34% (HOMA-IR, p < 0.001)." (PMID 39517207, 2024). "We found that daily oral administration of HF increases glucose tolerance whilst reducing weight gain, insulin resistance, and serum insulin in DIO mice." (PMID 39150520, 2024). "Fasting blood insulin level is an important biomarker for insulin resistance observed in overweight, obesity and metabolic syndrome, conditions related to cardiovascular risk." (PMID 38670169, 2024). "The term “insulin resistance” typically refers to the diminished responsiveness of cells, particularly in skeletal muscle, to normal levels of insulin." (PMID 38397999, 2024). "In the pre-DM stage, the patients already present with both insulin resistance (IR) and impaired insulin secretion from pancreatic islet β cells." (PMID 38763955, 2024). "Chronic exposure to pro-inflammatory cytokines, TNF-α, IL-6, and insulin-growth-factor-binding proteins (IGFBPs) has been reported to induce insulin resistance by directly impairing insulin signaling activation while simultaneously fueling tumor activation." (PMID 38791998, 2024). "Gestational diabetes mellitus is characterised by an insufficient insulin response to hyperglycaemia and the development of insulin resistance." (PMID 39518962, 2024). "Insulin resistance arises when tissues become less responsive to insulin signaling, which is characterized by impaired glucose uptake and oxidation, diminished glycogen synthesis, and a weakened capacity to suppress lipid oxidation." (PMID 39741881, 2024). "It was observed that synbiotic supplementation significantly reduced fasting plasma glucose, insulin levels, and insulin resistance while increasing insulin sensitivity compared with the placebo." (PMID 39599742, 2024). "Circadian clock disruption decreases insulin secretion, increases insulin resistance, and disrupts glucose homeostasis, contributing to T2D progression." (PMID 39165284, 2024). "Chronic inflammation resulting from insulin resistance and increased circulating free fatty acids are considered among the primary drivers of increased gluconeogenesis under insulin-resistant conditions." (PMID 38745315, 2024). "Dysregulation of the interaction between insulin-secreting cells and insulin-responsive target organs is an important factor driving the progression of insulin resistance." (PMID 39239539, 2024). "In the early stages of insulin resistance, insulin levels in cerebrospinal fluid increased following a rise in peripheral insulin levels." (PMID 39758348, 2024). "Almost similar findings were observed in studies demonstrating an improvement in the effects of GSE on insulin levels and insulin resistance." (PMID 38755622, 2024).
Insulin resistance (continued). "Insulin resistance represents a pathological state defined as a condition of lower insulin-targeting tissue responsiveness to insulin levels." (PMID 38159164, 2024). "Assessment of CB chemosensitivity through the classical Dejour’s test clearly shown that individuals with prediabetes exhibit increased CB chemosensitivity that correlates with insulin levels and insulin resistance." (PMID 38646610, 2024). "BCG vaccination significantly improved changes in fasting glucose and insulin levels, insulin resistance indexes, and glucagon-to-insulin ratios in conjunction with the HFD at the end of the experiment." (PMID 38929483, 2024). "The ability of resveratrol treatment to improve the insulin resistance is supported by animal studies reporting improvements in insulin sensitivity and insulin signal transduction." (PMID 38324260, 2024). "As a consequence of extreme insulin resistance and high circulating insulin levels, patients usually develop functional and structural defects in many body organs." (PMID 38773407, 2024). "HOMA-IR, a commonly used metric to assess insulin sensitivity, exhibits high sensitivity and specificity in measuring insulin resistance." (PMID 38505752, 2024). "Insulin resistance denotes a cellular state where responses to insulin, crucial for glucose uptake, diminish." (PMID 38441531, 2024). "Second, in a state of hyperinsulinemia induced by insulin resistance, insulin can promote sodium reabsorption and increase glomerular filtration rate, which can lead to renal damage." (PMID 38617935, 2024). "The increase in the level of adipokines (leptin), cytokines (TNF-α and IL-6), and non-esterified fatty acids in obese patients can block the action of insulin and help develop insulin resistance, which leads to T2DM." (PMID 38671840, 2024). "PTEN plays an important role in regulating insulin signaling which is affected under conditions of insulin resistance." (PMID 38966710, 2024). "Fasting plasma glucose, plasma insulin, and insulin resistance also decreased significantly after three months (p < 0.01), an effect that persisted at six months." (PMID 38166036, 2024). "Studies have shown that insulin resistance differs by sex and Tanner stage, as well as described that insulin sensitivity relates to the body composition changes occurring during puberty according to sex and Tanner stage." (PMID 39685744, 2024). "Severe insulin-resistant diabetes (SIRD) is characterized by obesity, severe insulin resistance, high insulin secretion, late onset, relatively low HbA1c levels, and a markedly increased risk of nephropathy." (PMID 39200982, 2024). "Insulin resistance is the damage to the physiological response of insulin-stimulated target tissues, most commonly the liver, muscles, and adipose tissue." (PMID 39138505, 2024). "Foz mice fed the HFD also showed high fasting glycemia despite high fasting insulin concentration demonstrating severe insulin resistance." (PMID 39206703, 2024). "At the molecular level, insulin resistance is characterized by inefficient insulin signal transduction in pathways from the insulin receptor (INSR) to the final targets of insulin." (PMID 39770980, 2024). "Dysregulation of carbohydrate, lipid, and protein metabolism, typical for T2DM, is followed by insulin resistance or impaired insulin secretion, or a combination of both." (PMID 39839113, 2024). "Similar to our previous study, this study also demonstrated a reduction in insulin resistance, repair of damaged beta cells and an increase in insulin secretion in diabetic rats after treatment with HESS." (PMID 39238175, 2024). "A homeostatic model assessment for insulin resistance (HOMA IR), homeostatic model assessment for β cell (HOMA-β), quantitative insulin sensitivity check index (QUICKI) for insulin resistance, and EQ-5D for quality of life were performed." (PMID 38674884, 2024). "Patients with insulin resistance often have high levels of both glucose and insulin circulating in the blood." (PMID 38254596, 2024).